HDAC8 (histone deacetylase 8)
Diseases named in the same sentence as HDAC8 in open-access papers (continued):
Sharing a sentence is not in itself a finding about the gene and the disease.
colon cancer (10 papers, 2014 to 2025). "Alteration of epigenetic enzymes is associated with the pathophysiology of colon cancer with an overexpression of histone deacetylase 8 (HDAC8) enzyme in this tissue." (PMID 30687400, 2018). "We also detected HDAC8 associations under constitutive conditions in colon cancer cells (open bars, peak region ‘h')." (PMID 25321483, 2014). "HDAC8 inhibition enhances sensitivity to doxo, whereas in colon cancer, HDAC8 represses pro-apoptotic genes and activates Jak2/Stat signaling." (PMID 40332124, 2025). "An interesting study on colon cancer stem cells showed that miR-93 inhibited proliferation and colony formation in colon cancer stem cells and that this suppressor effect was likely achieved via negatively targeting histone deacetylase 8 (HDAC8)." (PMID 31648231, 2019). "Among the HDAC enzymes, expression of HDAC8 is highly prevalent in colon cancer where its expression level is higher compared to healthy tissues." (PMID 30687400, 2018). "Studies have reported that HDAC8 inhibits apoptosis in colon cancer cells by repressing Bcl-2-modifying factor (BMF) transcription." (PMID 30687400, 2018). "Studies have shown that knockdown of HDAC8 inhibits the proliferation of various cancer cells including colon cancer cells." (PMID 30687400, 2018). "Studies have shown roles of HDAC3 or HDAC8 in colon cancer cells." (PMID 31083396, 2019). "Methylselenopyruvate is an α-keto acid metabolite of methylselenocysteine which acts as a histone deacetylase 8 (HDAC8) inhibitor that can restore Bcl2 modifying factor (BMF) downregulation and thereby activates apoptosis in colon cancer cells." (PMID 34950627, 2021). "Genomic analysis of colon cancer cells shows an increased expression of HDAC8 compared to normal cells." (PMID 30687400, 2018). "However, the ability of quercetin in inhibiting HDAC8 in colon cancer has not been reported." (PMID 30687400, 2018).
cervical cancer (9 papers, 2007 to 2023). A primary or metastatic malignant neoplasm involving the cervix. "Vanaja and coauthors found that HDAC8 targets tubulin in HeLa cervical cancer cells and that inhibition or silencing of HDAC8 impedes the migration of these cells." (PMID 38004560, 2023). "It has been also described that HDAC8 overexpression promotes proliferation in lung, colon, cervical cancer cells and in hepatocellular carcinoma." (PMID 33024443, 2020). "For example, overexpressed of HDAC8 in neuroblastoma, cervical cancer and esophageal squamous cell carcinoma has been significantly correlated with poor prognosis in patients." (PMID 33024443, 2020). "Since HDAC8 is known to be involved in female-specific cancers such as ovary, cervical and breast, we have used HeLa cervical cancer cells along with HEK 293 T normal cells so as to get an insight on its role in normal and cancer cells." (PMID 29716651, 2018). "Knockdown of HDAC8 using siRNA has shown to inhibit human lung, colon, and cervical cancer proliferation." (PMID 29716651, 2018). "Knockdown of HDAC8 by RNA interference inhibits growth of human lung, colon and cervical cancer cell lines, highlighting the importance of this HDAC subtype for tumour cell proliferation." (PMID 18000499, 2007). "Inhibition of HDAC8 is desirable, since knockdown of HDAC8 by RNA interference inhibits growth of human lung, colon and cervical cancer cell lines, highlighting the importance of this HDAC subtype in tumour cell proliferation." (PMID 18000499, 2007). "In addition, knockdown of HDAC8 by RNAi suppresses the growth of human lung, colon and cervical cancer cell lines, indicating the importance of HDAC8 for tumour cell proliferation." (PMID 34435400, 2021). "Our study signifies the role of HDAC8 as tubulin deacetylase in cervical cancer cells and therefore might be a better target in these cancers." (PMID 29716651, 2018). "After knockdown of HDAC8 using siRNA experiments, an interference in the cell cycle was observed, as well as an alteration in cellular migration and morphology, which pointed out that HDAC8i could be a useful target in cervical cancer cells." (PMID 33634093, 2020). "HDAC8 shows functional redundancy with HDAC6 when overexpressed in cervical cancer cells, HeLa, and deacetylaes ac-lys40 of alpha tubulin leading to cervical cancer proliferation and progression." (PMID 29716651, 2018).
acute myeloid leukemia (8 papers, 2017 to 2026). Acute myeloid leukemia (AML) is a group of neoplasms arising from precursor cells committed to the myeloid cell-line differentiation.
Obesity (8 papers, 2016 to 2026). Accumulation of substantial excess body fat. "In obesity‐induced MA, SFN prevents obesity‐related metabolic disorders by targeting the HDAC8‐PGC1α axis, thereby enhancing mitochondrial biogenesis and function, and it improves glucose and lipid metabolic dysregulation caused by a high‐fat diet." (PMID 39743857, 2025). "Histone deacetylase 8 (HDAC8) is directly upregulated by SREBP-1 where it is coexpressed in dietary obesity models of HCC." (PMID 35912181, 2022). "HDAC8 is activated by SREBP1, an insulin-responsive transcription factor, which activates the transcription of lipogenic genes, and HDAC8 deficiency in obesity-associated mouse models of NASH and HCC ameliorated insulin resistance, reducing triglyceride levels and tumour growth." (PMID 36612019, 2022). "Emerging evidence has demonstrated that obesity-induced metabolic pathways can deregulate chromatin modifiers such as histone deacetylase 8 to trigger undesired global epigenetic changes, thereby modifying gene expression program which contributes to oncogenic signaling." (PMID 27556491, 2016). "In mice with diet-induced obesity that develop steatohepatitis and liver tumors, histone deacetylase 8 (HDAC8) and SREBP-1 are co-expressed in tumor tissues, and HDAC8 is directly upregulated by SREBP-1." (PMID 38137501, 2023). "By adding 0.5% (w/w) HDAC8 and HDAC9 inhibitors to the culture medium, the GFP intensity in the transgenic bmm-expressing flies increased significantly compared with the control, indicating that obesity was suppressed." (PMID 27247940, 2016). "Furthermore, HDAC8 was directly up-regulated by the lipogenic transcription factor SREBP-1, and such positive relationship is highly consistent in dietary obesity models of NASH and HCC." (PMID 27556491, 2016).
pulmonary fibrosis (7 papers, 2019 to 2024). Chronic progressive interstitial lung disorder characterized by the replacement of the lung tissue by connective tissue, leading to progressive dyspnea, respiratory failure, or right heart failure. "Similar to the effects of HDAC3 inhibitor, selective inhibition of Hdac8 was also shown to ameliorate bleomycin-induced lung fibrosis in mice through the reduction of ECM synthesis." (PMID 35626663, 2022). "On the other hand, selective inhibition of HDAC3, HDAC6 or HDAC8 has recently been demonstrated to exert remarkable therapeutic effects in the bleomycin mouse model of lung fibrosis." (PMID 35626663, 2022). "HDAC8 expression is increased in idiopathic pulmonary fibrosis lung tissues and normal human lung fibroblasts treated with the fibrogenic cytokine, TGF-β1." (PMID 36231123, 2022). "Until now, most of the agents developed have selectivity for HDAC3, HDAC6 and HDAC8 and have been or are still currently evaluated in preclinical studies for cancer and lung fibrosis." (PMID 35626663, 2022). "A recent study showed that HDAC8 expression is increased in lung tissues of patients with idiopathic pulmonary fibrosis, while HDAC8 inhibition ameliorates pulmonary fibrosis." (PMID 33959033, 2021). "The HDAC8 gene is an exciting potential target because of its role in pulmonary fibrosis (PF) and its interaction with histone deacetylase (HDAC) inhibitors." (PMID 33318519, 2020). "HDAC8 also contributes to the pathogenesis of pulmonary fibrosis." (PMID 36231123, 2022). "In addition, the HDAC8 inhibitor NCC170 was shown to ameliorate idiopathic pulmonary fibrosis, in part, by increasing PPARγ expression." (PMID 31817161, 2019). "A study reported that HDAC8 expression increased in IPF lung tissue, indicating that HDAC8 expression contributes to pulmonary fibrosis and HDAC8 inhibition can treat IPF and other fibrotic lung diseases." (PMID 35111164, 2021).
developmental delay (6 papers, 2020 to 2024). "HDAC8 gene variants lead to severe cognitive delay with specific facial features like delayed closure of the anterior fontanelle, hooded eyelids, widely spaced eyes, broad nose, and happy personality." (PMID 38673696, 2024). "Although the developmental delays are significant, the absence of epileptic seizures and the child’s remarkably cheerful disposition are consistent with the manifestations of the HDAC8 variants previously reported in the literature." (PMID 38673696, 2024). "Line mutations in several KATs and KDACs, such as KAT6A, SMC3 (coding chromosome protein 3), and HDAC8 (coding histone deacetylase 8, SMC3 deacetylase), are related to developmental retardation, abnormalities, and mental disabilities." (PMID 32399051, 2020).
gastric cancer (6 papers, 2020 to 2024). A primary or metastatic malignant neoplasm involving the stomach. "HDAC8 is overexpressed in cancers such as gastric cancer, HCC, oral squamous cell carcinoma, and childhood acute lymphoblastic leukemia." (PMID 36231123, 2022). "Additionally, siRNA‐mediated depletion of HDAC8 has been found to increase the rate of apoptosis in gastric cancer cells." (PMID 39317961, 2024). "Univariate Cox regression analysis revealed that HDAC1, HDAC5, HDAC8, SIRT3, and SIRT6 were significant predictors of gastric cancer." (PMID 37649598, 2023).
Insulin resistance (6 papers, 2016 to 2025). Increased resistance towards insulin, that is, diminished effectiveness of insulin in reducing blood glucose levels. "Specifically, HDAC3 and HDAC8 have been implicated in promoting insulin resistance and β‐catenin activation in MASLD‐associated HCC, while inhibition of HDAC2 and HDAC3 has been shown to ameliorate hepatic steatosis and inflammation in experimental models." (PMID 40693828, 2025). "Lentivirus-mediated silencing of HDAC8 in vivo was sufficient to reverse insulin resistance and reduce NAFLD-associated tumorigenicity." (PMID 27556491, 2016). "Activated HDAC8 can endorse Wnt signalling components resulting development of insulin resistance and glucose accumulation." (PMID 34071497, 2021). "HDAC8 has been recently reported to promote insulin resistance and activate Wnt/β-catenin pathway in a NAFLD-HCC mouse model treated with high fat high carbohydrate diet." (PMID 27556491, 2016). "Previous studies showed that HDAC6 and HDAC8 promoted insulin resistance in animal models." (PMID 36118901, 2022). "These suggest the possible role of HDAC8 in elevating insulin resistance and diabetes." (PMID 33096729, 2020).
liver cancer (6 papers, 2018 to 2025). An epithelial or non-epithelial malignant neoplasm that arises from the liver. "Overexpression of monopolar spindle 1 (MPS1) and histone deacetylase 8 (HDAC8) is associated with the proliferation of liver cancer cells, so simultaneous inhibition of both MPS1 and HDAC8 could offer a promising therapeutic approach for the treatment of liver cancer." (PMID 39351092, 2024). "AHR or HDAC8 overexpression in liver cancer cells speeds cell proliferation." (PMID 29301348, 2018). "Studies have shown that the selective HDAC8 inhibitor PCI-34051, when used alone, exhibits inhibitory effects on liver cancer." (PMID 40573881, 2025). "Consistently, HDAC8 inhibitors PCI-34051 and agonist TM-2-51 inhibited and promoted the growth of liver cancer cells, respectively." (PMID 33279948, 2020). "Application of DLPTP to 2D-TPP datasets profiling the HDAC8 inhibitor PCI-34051 and its analog BRD-3811 let us discover that both compounds inhibit LAP3, an interesting ovarian and liver cancer target." (PMID 33188197, 2020). "When liver cancer cells or mouse liver cells are treated with TCDD, a ligand of AHR, nuclear translocation of AHR turns on downstream genes, including HDAC8." (PMID 29301348, 2018).
prostate carcinoma (6 papers, 2015 to 2024). A carcinoma that arises from epithelial cells of the prostate gland. "In prostate cancer, HDAC8 promotes cancer metastasis by repressing the expression of maspin, a tumor suppressor that regulates cell migration and invasion." (PMID 36231123, 2022). "We analyzed the expression of DNMT1, DNMT3A, DNMT3B, and the class I HDACs HDAC1, HDAC2, HDAC3, and HDAC8 in the PRAD and Taylor data sets and their correlation to HLA-I expression in prostate cancer." (PMID 36050516, 2022). "For example, compound 11b, an indomethacin-SAHA fusion molecule that selectively inhibits COX2 and HDAC6 > HDAC8 > HDAC3 > HDAC2 > HDAC1, inhibits the proliferation of androgen-dependent prostate carcinoma cells." (PMID 31561534, 2019).
renal fibrosis (6 papers, 2016 to 2024). A final common manifestation of a wide variety of chronic kidney diseases characterized by glomerulosclerosis and tubulointerstitial fibrosis. "Recently, the role of HDAC8 in renal fibrosis has been highlighted, suggesting its potential as a target for AKI and CKD." (PMID 36077415, 2022). "In UUO-induced renal fibrosis mice model, the HDAC8 inhibitor, PCI34051, inhibited Smad3, STAT3, β-catenin and Snail expressions and activated BMP7 and Klotho renal protective protein expressions." (PMID 35250597, 2022). "Similarly, it has been reported that inhibition of HDAC3 and HDAC8 derepressed klotho expression during renal fibrosis." (PMID 38794880, 2024). "Recent reports have indicated the potential involvement of HDAC8 in renal fibrosis." (PMID 39317961, 2024). "Following these latter findings, previous work evidenced that HDAC8 inhibition with 1 could modulate the expression of profibrotic markers, attenuating renal fibrosis induced by unilateral ureteral obstruction in vivo and TGF-β1 exposure in vitro." (PMID 36077415, 2022). "Even though our findings require further confirmatory in vivo studies, use of class I‐selective HDAC inhibitors or HDAC8 knockdown could be a useful therapeutic strategy for the treatment of renal fibrosis." (PMID 27420561, 2016). "In a murine model of renal fibrosis induced by UUO, HDAC8 was also detected in both cellular components of renal epithelial cells and its expression levels increased over time." (PMID 39317961, 2024). "Additionally, our recent study showed upregulation of HDAC8 in the kidneys of a murine model with renal fibrosis induced by unilateral ureteral obstruction (UUO), and administration of PCI‐34051 attenuated renal fibrosis." (PMID 39317961, 2024). "Since HDAC8 is primarily expressed in renal epithelial cells, but not renal interstitial fibroblasts, HDAC8 may induce renal fibrosis by triggering EMT and release of profibrotic growth factors/cytokine, subsequently leading to renal fibroblast/pericyte activation and renal fibrosis." (PMID 35559244, 2022).
T-cell lymphoma (6 papers, 2014 to 2024). "HDAC8 is expressed specifically during TH17 development, and inhibition of HDAC8 induces apoptosis of T-cell lymphoma cells." (PMID 30034392, 2018). "The distinctive structure of HDAC8, in comparison to others class I HDAC family members, allowed the development of high specific HDAC8 inhibitor PCI-34051 (hereafter PCI), previously tested in T-cell lymphoma and AML." (PMID 33015043, 2020). "HDAC8 may be linked to PLCγ1, a signal transducer, absent activation and subsequent failure to release intracellular Ca2+ and reactive oxygen species (ROS) in cutaneous T-cell lymphoma cells, suggesting that HDAC8 may play a role in the induction of apoptosis in T cell lymphomas." (PMID 28624794, 2017).
viral infection (6 papers, 2017 to 2025). "Our previous research showed that HDAC8 (histone deacetylase 8) involved in innate antiviral immune response, but the underlying mechanism during virus infection is still unclear." (PMID 39035358, 2024). "HDAC8 has also been involved in other pathological conditions including cancer, parasitic and viral infections, where it has mainly been shown to contribute to the pathology through its deacetylase activity." (PMID 39779705, 2025). "With the finding of more and more HDAC8 specific inhibitors, these findings provided a potential therapeutic strategy for the prevention and control of viral diseases." (PMID 39035358, 2024). "Viral infection increases the risk of PF27 and it is reported that HDAC8 inhibition ameliorates PF28; moreover we found that cigarette exposure, a known risk factor for both COVID-19 and IPF, increases the expression of HDAC8 in lung tissue." (PMID 33318519, 2020). "In parasitic and viral infection, HDAC8 is required for centrosome cohesion and virus entry, and down-regulation of HDAC8 expression in schistosomula results in a decreased capability of their survival and maturation in infected mice." (PMID 28223544, 2017). "HDAC8 is a zinc dependent class I histone deacetylase that plays a critical role in a wide aspects of biological processes, ranging from transcriptional regulation, sister chromatid separation, virus infection, energy homeostasis to smooth muscle contraction." (PMID 28223544, 2017). "We found that viral infection-induced TOB1 interacted with IRF3 and bound to the promoter region of Ifnb1, leading to recruitment of HDAC8 and suppression of IFN-β production." (PMID 36085336, 2022). "Histone deacetylase 8 (HDAC8) is one of the class I HDAC family proteins, which participates in the neuronal disorders, parasitic/viral infections, tumorigenesis and many other biological processes." (PMID 34435400, 2021). "Based on sequence homology, histone deacetylase 8 (HDAC8) is one of the class I HDAC enzymes, which plays important roles in parasitic/viral infections, tumorigenesis, neuronal disorders, smooth muscle contraction, skull morphogenesis, telomere protection and cohesin dynamics." (PMID 34435400, 2021).